APLF (aprataxin and PNKP like factor)
Description:
Histone chaperone involved in single-strand and double-strand DNA break repair. Recruited to sites of DNA damage through interaction with branched poly-ADP-ribose chains, a polymeric post-translational modification synthesized transiently at sites of chromosomal damage to accelerate DNA strand break repair reactions. Following recruitment to DNA damage sites, acts as a histone chaperone that mediates histone eviction during DNA repair and promotes recruitment of histone variant MACROH2A1. Also has a nuclease activity: displays apurinic-apyrimidinic (AP) endonuclease and 3'-5' exonuclease activities in vitro. Also able to introduce nicks at hydroxyuracil and other types of pyrimidine base damage. Together with PARP3, promotes the retention of the LIG4-XRCC4 complex on chromatin and accelerate DNA ligation during non-homologous end-joining (NHEJ). Also acts as a negative regulator of cell pluripotency by promoting histone exchange (By similarity). Required for the embryo implantation during the epithelial to mesenchymal transition in females (By similarity).
Synonyms: C2orf13; PALF; XIP1; MGC47799; ZCCHH1; APFL
Tractability: Small molecule: a structure with a bound ligand is known.
Gene: Protein-coding gene on chromosome 2 (68,467,572 to 68,655,862, forward strand). Ensembl gene ENSG00000169621.
Subcellular location: Nucleus; Chromosome; Cytoplasm, cytosol
Subcellular location (Human Protein Atlas): Nucleoplasm
Gene Ontology:
Molecular function: 3'-5' exonuclease activity; ADP-D-ribose modification-dependent protein binding; DNA endonuclease activity; DNA-(apurinic or apyrimidinic site) endonuclease activity; histone binding; histone chaperone activity; nucleotide binding; poly-ADP-D-ribose binding; protein binding; protein folding chaperone
Biological process: DNA damage response; DNA repair; DNA repair-dependent chromatin remodeling; double-strand break repair; double-strand break repair via nonhomologous end joining; protein localization to chromatin; single strand break repair; embryo implantation; regulation of DNA repair; regulation of epithelial to mesenchymal transition; protein folding
Cellular component: chromosome; nucleoplasm; nucleus; site of DNA damage; site of double-strand break; DNA ligase III-XRCC1 complex; cytosol
Genetic constraint (gnomAD): Loss-of-function variants: 54 observed, 46.68 expected, observed/expected ratio (o/e) 1.16, 90% interval 0.93 to 1.45. The upper end of that interval is the gene's LOEUF score, 1.45, which puts it in group 5 of 6, group 1 being the genes least tolerant of losing a copy. Missense variants: 549 observed, 548.31 expected, observed/expected ratio (o/e) 1, 90% interval 0.93 to 1.07. Synonymous variants: 192 observed, 196.63 expected, observed/expected ratio (o/e) 0.98, 90% interval 0.87 to 1.1.
Homologues: Orthologues: chimpanzee APLF (98% identical), macaque APLF (95% identical), pig APLF (77% identical), rabbit APLF (73% identical), dog APLF (72% identical), guinea pig APLF (66% identical), mouse Aplf (60% identical), rat Aplf (59% identical), tropical clawed frog aplf (38% identical), Drosophila melanogaster CG6171 (13% identical), zebrafish aplf (12% identical).
Diseases named in the same sentence as APLF in open-access papers:
APLF is named in the same sentence as 16 diseases in open-access papers, as found by Europe PMC text mining. Sharing a sentence is not in itself a finding about the gene and the disease. The quoted sentences say what the papers report.
breast carcinoma (3 papers, 2018 to 2022). "Rationale for choosing APLF and HJURP amongst all other histone chaperones is that, APLF over-expression is associated with TNBC/basal type breast cancer metastasis while HJURP over-expression is associated with luminalA breast cancer metastasis." (PMID 32257110, 2020). "We investigated the role of APLF in epithelial-to-mesenchymal transition (EMT) linked to breast cancer invasiveness and metastasis." (PMID 29580241, 2018). "Further, APLF suppression promotes breast cancer and bladder cancer invasiveness through inhibition of proliferative capacity, altered cell cycle behavior, induced apoptosis, and impaired DNA repair ability." (PMID 36497496, 2022). "In short, APLF expression was directly proportional to the degree of metastatic nature of the breast cancer cells." (PMID 32257110, 2020).
breast tumors (1 paper, 2018). "So, here we provided novel evidence for enrichment of APLF in breast tumors, which could regulate metastasis-associated EMT in invasive breast cancer." (PMID 29580241, 2018). "We anticipate that APLF could be exploited as a biomarker for breast tumors and additionally could be targeted in sensitizing cancer cells towards DNA damaging agents." (PMID 29580241, 2018).
gastric cancer (1 paper, 2022). A primary or metastatic malignant neoplasm involving the stomach. "Taken together, these findings revealed that the radiotherapy or chemotherapy promoted the expression of DNA repair genes (APLF, EID3, EME2, NPAS2 and POLN) of gastric cancer non-stem stem cells to trigger DNA repair, resulting in the biogenesis of GCSCs." (PMID 36153608, 2022).
hepatocellular carcinoma (1 paper, 2023). A malignant tumor that arises from hepatocytes. "In hepatocellular carcinoma (HCC), the novel lncRNA NIHCOLE acts as a scaffold and facilitates the formation of multimeric complexes involving Ku70/80, APLF, XRCC4, and DNA ligase IV to promoting the ligation efficiency of DNA DSBs." (PMID 38012734, 2023).
invasive breast carcinoma (1 paper, 2018). A carcinoma that infiltrates the breast parenchyma. "APLF was significantly induced in triple negative breast cancer (TNBC) cells, MDAMB-231, in comparison to invasive MCF7 or normal MCF10A breast cells and supported by studies on invasive breast carcinoma in The Cancer Genome Atlas (TCGA)." (PMID 29580241, 2018).
cancer (4 papers, 2015 to 2024). A tumor composed of atypical neoplastic, often pleomorphic cells that invade other tissues. "Downregulation of APLF (Aprataxin and PNK-like factor) inhibited cancer cell proliferation, altered cell cycle behavior, induced apoptosis, and impaired DNA repair ability." (PMID 39202384, 2024). "Besides, we observed varying expression of APLF, BRCA1, WRN and LIGASE I in normal and cancer cells." (PMID 25789972, 2015). "Moreover, guardians of genome stability involved in cancer such as SWItch/Sucrose non-fermentable (SWI/SNF) helicase, α-thalassemia/MR, X-linked (ATRX) and aprataxin-PNK-like factor (APLF) act as negative and positive regulators, respectively, of macroH2A1’s chromatin association." (PMID 29206173, 2017).
tumor (3 papers, 2023 to 2025). "A similar result was obtained by analysing the GSE121248 and GSE33006 datasets from the GEO database, and nearly all H3–H4 histone chaperones were significantly overexpressed in tumor tissues, except for APLF, HIRA and NASP." (PMID 38561384, 2024).
psychiatric disease (1 paper, 2024). "Within our dataset, genes with shifted aging trajectories in psychiatric disease include APLF (in Exc_L2–L3, Exc_L4–L6_1 and Exc_L4–L6_2 neurons), EXPH5 (in Exc_L2–L3 and Exc_L4–L6_3 neurons) and RHBDL3 (in Exc_L4–L6_2 neurons)." (PMID 39227716, 2024). "APLF is one of the genes with the strongest decrease with age and reduction in individuals with psychiatric disease across cell types." (PMID 39227716, 2024).
APLF also shares sentences with these, for which no sentence is quoted: bladder cancer (1 paper); epithelial ovarian cancer (1); Fanconi anemia (1); glioblastoma (1); glioma (1); Hepatitis (1); triple-negative breast carcinoma (1); Werner syndrome (1).